PARG (poly(ADP-ribose) glycohydrolase)
Diseases named in the same sentence as PARG in open-access papers (continued):
Sharing a sentence is not in itself a finding about the gene and the disease.
ovarian carcinoma (continued). "Although PARG inhibitors have not yet reached clinical trials, they have shown synergistic effects with CHK1 inhibitors in ovarian cancer cell lines and ovarian PDX models." (PMID 32029455, 2020). "Interestingly, when screening ovarian cancer cell lines for sensitivity to the PARGi PDD00017273, cells that were differentially sensitive to PARG but not PARP inhibition were identified." (PMID 33005627, 2020).
pancreatic cancer (9 papers, 2014 to 2023). "Furthermore, PARG deficient −/− embryonic stem cells and PARG depleted pancreatic cancer cells exhibited S-phase arrest and increased DNA damage when treated with the alkylating agent MMS." (PMID 33005627, 2020). "Pancreatic cancers were divided into Cluster 1 (C1) and Cluster 2 (C1) according to PARG mRNA expression." (PMID 37124502, 2023). "Cell death induced by ZZW-115 treatment of pancreas cancer-derived cells is rescued by olaparib and improved with PARG inhibitor PDD00017273." (PMID 35869257, 2022). "It has recently been reported that PARG impacts the response to PARPi in models of pancreatic cancer." (PMID 30467127, 2018). "In addition, HuR can bind to PARG mRNA under the stimulation of PARP inhibitors, and the inhibition of HuR binding to PARG mRNA helps to improve PARP inhibition therapy in pancreatic cancer cells." (PMID 31500199, 2019). "Furthermore, HuR can bind PARG mRNA under PARP inhibitor stress, and the inhibition of HuR combined with PARG mRNA helps to improve the effectiveness of PARP inhibitory therapy in pancreatic cancer cells." (PMID 31055645, 2019).
colon carcinoma (5 papers, 2016 to 2025). "Although RNAi-mediated silencing of PARG in colon cancer cells increases the level of phosphorylated Akt, PARG silencing still inhibits metastatic potential due to decreased expression of NF-κB, MMP-2, and MMP-9." (PMID 33923319, 2021). "Silencing of PARG by shRNA decreased the proliferation rate twofold over wild type LoVo colon cancer cells." (PMID 32344695, 2020). "The mRNA and protein levels of PARG, PARP1, and NF-κB p65 were downregulated by BXD, suggesting that BXD may suppress the malignant characteristics of colon cancer cells by modulating the PARG/PARP1/NF-κB signaling pathway." (PMID 41305005, 2025). "PARG is vital to tumor growth and metastasis of colon carcinoma and may be applied as a new target for treating colon carcinoma." (PMID 35806303, 2022). "PARG depletion was shown to affect cell proliferation of LoVo colon cancer cells line." (PMID 27375368, 2016).
glioblastoma (5 papers, 2019 to 2025). The most malignant astrocytic tumor (WHO grade IV). "To further support the potential relevance of our findings to the cell types more related to neurodegeneration, we assessed the effect of ARH3 loss on the sensitivity of glioblastoma U251 cells to PARG and PARP inhibition." (PMID 34019811, 2021). "In PARP inhibitor-resistant A172 glioblastoma cells, our PARG inhibitor shows comparable killing to Nedaplatin, providing further proof-of-concept that selectively inhibiting PARG can impair cancer cell survival." (PMID 31827085, 2019). "Although the distance between PARG and SHLD2 is longer in the human genome (37 versus 2 MB), both genes are located on chromosome 10q, and recurrent arm-level deletions in this region have been reported in multiple cancer types, such as lymphomas, glioblastoma, and lung cancer." (PMID 37209095, 2023).
hepatocellular carcinoma (5 papers, 2014 to 2024). A malignant tumor that arises from hepatocytes. "PARG is overexpressed in various malignant diseases, such as hepatocellular carcinoma and cancers of the oesophagus, endometrium, colon and rectum, and ovaries (Refs 59–63)." (PMID 39375922, 2024). "Interestingly, in hepatocellular carcinoma, high levels of both PARP1 and PARG are associated with an unfavorable prognosis." (PMID 38139034, 2023). "Mechanistically, PARG dePARylates damage-specific DNA binding protein 1 (DDB1), thereby up-regulating its auto-ubiquitination and decreasing its stability in hepatocellular carcinoma cells (Ref." (PMID 39375922, 2024). "In a recent report where immunotherapy was used for patients with advanced hepatocellular carcinoma (HCC), PARG inhibition was shown to have a synergistic effect with anti-programmed cell death 1 (PD1) therapy." (PMID 37858678, 2023). "In hepatocellular carcinoma (HCC) cells, PARG O-GlcNAcylation enhances the poly(ADP-ribosyl)ation of DNA damage-binding protein 1 (DDB1) and attenuates its auto-ubiquitination, thereby stabilizing DDB1 and allowing it to degrade its downstream targets, such as c-Myc." (PMID 37858678, 2023).
melanoma (5 papers, 2013 to 2025). A malignant, usually aggressive tumor composed of atypical, neoplastic melanocytes. "Similar effects utilizing PARG inhibitors or the RNAi knockdown of PARG were observed, where PARG silencing or inhibition led to radiation-induced mitotic catastrophe, chemosensitization in malignant melanoma cells and targeted cell death in BRCA2-deficient tumor cells." (PMID 23254695, 2013). "Malignant glioma, lymphoma, melanoma, renal, prostate and testis cancers were mostly negative for anti-PARG antibody staining as posted on Protein Atlas database." (PMID 35585513, 2022).
serous ovarian cancers (5 papers, 2019 to 2025). "PARPis are widely used in clinical treatment, and PARG inhibitors show promising results in vitro for high-grade serous ovarian cancer cells." (PMID 39615107, 2025). "Mechanistically, we uncovered that PARG loss mediates PARPi resistance by partially restoring PARP1 signaling, and we observed that biopsies of TNBC and high serous ovarian carcinoma patients carry a substantial percentage of tumor cells with low expression of PARG and increased PARylation." (PMID 38360994, 2024). "Thus, PARG/CHK1 inhibitor combinations may have promise in both high-grade and low-grade serous ovarian cancers and may offer an early intervention for patients with platinum-refractory disease." (PMID 30889383, 2019).
breast tumor (4 papers, 2019 to 2024). "Genetic screening has confirmed that PARG deficiency induced PARPi resistance in mouse breast tumor cells, and even this mechanism was relatively common in BRCA2-deficient mouse breast tumor cell resistance." (PMID 39318358, 2024). "Overall, these results show that PARG expression is deregulated in breast tumor tissues, and it appears that high PARG protein is observed approximately fivefold more frequently in tumor tissues than normal epithelium." (PMID 30459355, 2019). "In addition, a multicomponent analysis of breast tumors in genetically screened PARPi-sensitive and drug-resistant BRCA2 mutated mice determined that depletion of PAR glycohydrolase (PARG) restores PAR formation and partially rescues PARP1 signaling." (PMID 39318358, 2024). "PARG expression was also detected in a majority or most of ovarian and breast tumor samples." (PMID 38578205, 2024). "Using a Brca2 mouse model of breast tumors, Gogola and colleagues showed that inactivation of poly(ADP-ribose) glycohydrolase (PARG), which catalyzes PARP poly(ADP–ribose) degradation, is another mechanism of acquired resistance to PARP inhibition." (PMID 33923105, 2021).
colorectal cancer (4 papers, 2016 to 2025). A primary or metastatic malignant neoplasm that affects the colon or rectum. "We previously investigated resistance mechanisms to the PARG inhibitor PDD00017273 in human colorectal cancer HCT116 cells and established an acquired PDD00017273-resistant HCT116RPDD cell line." (PMID 41347713, 2025). "In conclusion, our findings suggest that resistance to the selective PARG inhibitor PDD00017273 induces PARG mutation and PARP downregulation in human colorectal cancer HCT116 cells." (PMID 36053937, 2023). "In order to elucidate the mechanisms underlying resistance to the PARG inhibitor PDD00017273, a PDD00017273‐resistant variant of the HCT116 human colorectal cancer cell line was developed." (PMID 36053937, 2023). "Other candidates, PARG and TDGF1, have been associated with cancer regulation; however, the functional role of the candidates HORMAD1, PIGC, NCAM2, INO80D, SLCO2A1, SLC12A1, and METTL19 was unclear in colorectal cancer." (PMID 27383761, 2016).
lung carcinoma (4 papers, 2018 to 2023). "It suggested that loss of PARG stabilized the expression of Wnt ligands, probably suppressing the activation of the Wnt pathway against the progression of lung cancer." (PMID 31130856, 2019). "In this study, it is shown that PARG gene silencing can prevent the occurrence of lung cancer induced by BaP." (PMID 31130856, 2019). "We will try to explore how does PARG regulates protein tyrosine phosphorylation to regulate the Wnt signaling against the progression of lung cancer in our next study." (PMID 31130856, 2019). "In concludsion, the use of Wnt ligands in the diagnosis of lung cancer and the use of PARG inhibitors as a potential therapeutic against lung cancer is supported." (PMID 31130856, 2019). "The heterozygous PARG knockout mice were used to characterize the role of PARG in protecting mice from BaP-induced lung cancer." (PMID 31130856, 2019). "To establish a lung cancer model for assessing the effects of heterozygous PARG silencing, we exposed mice to long-term inhalation of BaP and then prepared paraffin sections of lung tissues." (PMID 31130856, 2019). "For example, enhanced G2/M checkpoint arrest is seen in PARG depleted HeLa cells, while abrogation of this arrest is reported in lung cancer cells." (PMID 29179156, 2018). "On the basis of our findings, PARG gene and Wnt ligands may constitute a new option for the diagnosis and treatment of lung cancer." (PMID 31130856, 2019). "The purpose of this study was to investigate whether PARG gene silencing can inhibit lung cancer development induced by BaP and whether it can regulate the Wnt ligands to inhibit the development of lung cancer." (PMID 31130856, 2019). "Our results demonstrate that PARG may be a target for the diagnosis and treatment of lung cancer." (PMID 31130856, 2019). "Our work provides initial evidence that PARG silencing suppresses BaP induced lung cancer and stabilizes the expression of Wnt ligands, PARG gene and Wnt ligands may provide new options for the diagnosis and treatment of lung cancer." (PMID 31130856, 2019). "The silencing of CCL7, which was downregulated 2-fold due to PARG’s overexpression, was shown to reduce experimental liver metastasis, whereas CCL5 silencing (downregulated 4-fold in our experiments) reduced metastasis of non-metastatic lung carcinoma cells." (PMID 35585513, 2022).
prostate carcinoma (4 papers, 2017 to 2021). A carcinoma that arises from epithelial cells of the prostate gland. "In summary, we show that androgen receptor signaling stimulates DNA repair in part through increasing basal levels of PARG expression, suggesting a novel therapeutic target for prostate cancer patients with advanced disease." (PMID 32123273, 2020). "We have demonstrated that PARG inhibition can robustly strengthen the response to androgen deprivation and increase DNA damage in prostate cancer cells by reducing BER capacity." (PMID 32123273, 2020). "This presents a therapeutic opportunity for exploring PARG inhibitors as a supplemental therapy to prostate cancer therapies such as castration, chemotherapy, and radiation." (PMID 32123273, 2020). "In this report, we tested whether androgen deprivation synergized with PARG inhibition to suppress prostate cancer cell growth." (PMID 32123273, 2020). "Thus, combination of androgen ablation and PARG inhibition synergizes to reduce BER capacity in androgen dependent prostate cancer cells." (PMID 32123273, 2020). "Consistently, in primary prostate cancer LuCaP35 xenografts tumors, intratumoral PARG expression declined in males 4 weeks after castration when compared to tumors from SHAM operated animals which underwent all surgical procedures except removal of the testicles [GSE33316]." (PMID 32123273, 2020). "Furthermore, AR regulation of PARG expression was confirmed by quantitative RT-PCR and western blotting in two independently derived prostate cancer cell lines." (PMID 32123273, 2020). "Thus, AR and PARG are engaged in reciprocal regulation suggesting that the success of androgen ablation therapy can be enhanced by PARG inhibition in prostate cancer patients." (PMID 32123273, 2020). "If this scenario also holds true in prostate cancer, our study may warrant further investigation of whether BTF3 silencing-induced DNA replication vulnerability sensitizes cells to PARG inhibition, a potential new treatment strategy that can be extended to treat prostate cancer patients." (PMID 33414468, 2021). "With prostate cancer progression to CRPC, AR levels and transcriptional outputs are significantly increased with a corresponding elevation of PARG expression." (PMID 32123273, 2020). "We found that inhibition of PARG synergized with androgen deprivation to reduce BER capacity and inhibit cellular proliferation and viability in multiple prostate cancer cell lines." (PMID 32123273, 2020). "Androgen ablation combined with PARG inhibition synergistically reduces BER capacity in independently derived LNCaP and LAPC4 prostate cancer cell lines." (PMID 32123273, 2020). "A thorough evaluation of PARG function in prostate cancer was hampered by a lack of stable and bioavailable inhibitors." (PMID 32123273, 2020). "While PARP1 levels are not regulated by AR, PARG inhibition has a potential to synergize with castration therapy and be more effective in reducing cancer burden in men with advanced prostate cancer." (PMID 32123273, 2020). "PARG mRNA expression was upregulated in the presence of the synthetic androgen methyltrienalone (R1881) in LNCaP cells and with DHT treatment in the independently derived LNCaP and LAPC4 prostate cancer cell lines." (PMID 32123273, 2020). "While PARP inhibitors have been tested in clinical trials and are a promising therapy for prostate cancer patients with TMPRSS2-ERG fusions and mutations in DNA repair genes, PARG inhibitors have not been evaluated." (PMID 32123273, 2020). "While a number of clinical trials are ongoing to evaluate PARP1 inhibition as a prostate cancer therapy, PARG inhibition as a therapeutic strategy has not yet been tested." (PMID 32123273, 2020).
breast adenocarcinoma (3 papers, 2012 to 2015). "We successfully decreased AIF and PARG protein levels in the MDA-MB-231 breast adenocarcinoma cells by RNAi." (PMID 26178079, 2015). "We previously demonstrated that the RNAi knockdown of PARG surprisingly led to the increased survival of MCF-7 breast adenocarcinoma cells in response to chemo-therapeutic treatments." (PMID 23254695, 2013). "Taken together, these results demonstrate that AIF can substitute as the primary mediator of cell death in PARG-silenced MDA-MB-231 cells in the absence of caspases, and it potentially identifies a critical role for AIF in the death of breast adenocarcinoma cells after chemotherapy." (PMID 22839996, 2012).
glioma (3 papers, 2020 to 2021). A benign or malignant brain and spinal cord tumor that arises from glial cells (astrocytes, oligodendrocytes, ependymal cells). "By sequestering NAD+ in stabilised PAR chains, PARG inhibition was recently shown to cause metabolic catastrophe in glioma cell lines harbouring IDH1 mutations." (PMID 34656146, 2021). "A standard therapeutic approach for glioma is ionizing radiation (IR) and so we first evaluated the impact of the PARG inhibitor PDD00017273 on the IR response of GSCs." (PMID 34806016, 2021). "Elevated expression of the DNA damage response proteins PARP1 and poly(ADP-ribose) glycohydrolase (PARG) in glioma stem cells (GSCs) suggests that glioma may be a unique target for PARG inhibitors (PARGi)." (PMID 34806016, 2021). "In fact, PARG activity is reported to be high in C6 glioma tumor cells." (PMID 32344695, 2020). "While as much as 40% of the glioma stem cells showed positive EdU incorporation following either DMSO, NRH or PARG inhibitor treatment, there was only a minimum EdU signal (< 5%), close to the negative control (2%), in the NRH/PARGi-treated cells, indicating a block to DNA replication." (PMID 34806016, 2021). "Consistently, we find that while PARG inhibition (10 μM) alone promotes <30% cell death in both GSC-83 and GSC-326 cells, the addition of a non-toxic dose of NRH (100 μM), and the resulting increase in cellular NAD+ levels, results in near 100% cell killing in multiple glioma stem cell lines." (PMID 34806016, 2021).
liver cancer (3 papers, 2014 to 2024). An epithelial or non-epithelial malignant neoplasm that arises from the liver. "The aim of this preclinical study was to evaluate the expression of PARP and PARG genes in a panel of liver cancer cell lines and primary human hepatocytes, their DNA repair capacity and assess the impact on cell survival of PARP inhibitors alone and in combination with radiotherapy." (PMID 25139788, 2014). "The authors noted that the oncogenic poly(ADP-ribose) glycohydrolase (PARG) influences DDB1 stability, and suggested a role for the PARG–DDB1 interplay in HBV infection and liver cancer development." (PMID 38757942, 2024). "To investigate the tumor-forming potential of liver cells lacking PARG, we employed a chemically-induced liver cancer model." (PMID 38139034, 2023).
thyroid cancer (3 papers, 2020 to 2025). "Among those types of cancers that are available for this analysis, lower PARG expression was detected for three types of kidney cancer: kidney chromophobe, renal clear cell carcinoma, renal pappilary carcinoma, and for thyroid carcinoma." (PMID 35585513, 2022).
Clear Cell Renal Cell Carcinoma (2 papers, 2021 to 2022). "We have shown that the development of clear cell renal cell carcinoma (ccRCC) is associated with extreme accumulation of pADPr caused by the enhanced expression of PARP-1 and decreased PARG levels." (PMID 34638458, 2021). "Following these studies, our recently published data on clear cell renal cell carcinoma (ccRCC) demonstrated that upregulation of PARG reduces the clonogenic activity ccRCC cells in vitro, which is also associated with downregulation of genes associated with a number of tumorigenic pathways." (PMID 35585513, 2022). "We have shown that Clear Cell Renal Cell Carcinoma (ccRCC) is prone to accumulate poly(ADPribose) due to increase in PARP-1 and decrease in PARG enzymes." (PMID 34638458, 2021).
head and neck cancer (2 papers, 2024 to 2025). A primary or metastatic malignant neoplasm affecting the head and neck. "Our results suggest OGG1 and PARG play a fundamental role in the cellular response to CDD and indicate that targeting these enzymes could represent a promising therapeutic strategy for the treatment of head and neck cancers following high-LET radiation." (PMID 38368415, 2024).
leukemia (2 papers, 2016 to 2021). A malignant (clonal) hematologic disorder, involving hematopoietic stem cells and characterized by the presence of primitive or atypical myeloid or lymphoid cells in the bone marrow and the blood. "We have examined a large number of cancer and normal cells of various origins (kidney, breast, ovarian, prostate, and leukemia) for aberrations in the poly(ADP-ribosyl)ating pathway, including PARP-1 protein and PARG enzyme." (PMID 34638458, 2021). "Using a high-throughput combination chemical screen, we identified that the poly(ADP-ribose) glycohydrolase (PARG) inhibitor ethacridine lactate synergized with ibrutinib in TEX and OCI-AML2 leukemia cell lines." (PMID 26624983, 2016).
ovarian tumor (2 papers, 2024 to 2025). "Another study showed that 60 of 274 (22%) of human ovarian tumors have low PARG expression." (PMID 38578205, 2024).